H2AX (H2A.X variant histone)
Diseases named in the same sentence as H2AX in open-access papers (continued):
Sharing a sentence is not in itself a finding about the gene and the disease.
cancer (continued). "Conversely, neither the PAR nor γ-H2AX protein was noted in the A549 NQO1-knockout cells after IP-DNQ treatment, indicating that IP-DNQ kills cancer cells in an NQO1-dependent manner." (PMID 38136388, 2023). "In addition, as DNA damage response has been proved to provoke the induction of chemoresistance in human cancer cells, we evaluated the association between SCD1 expression and DNA damage biomarkers, such as positive modulator MGMT and negative modulator γ-H2AX." (PMID 29354058, 2017). "In ten cancer patients that experienced little or no NTT and in seven normal (noncancer controls), efficient repair of DNA DSB was observed in the γ-H2AX assay." (PMID 21491423, 2011). "The results showed that compared with non-radiation, more γ-H2AX foci were observed in PCI-34051 and radiation treated A549 cancer cells, HepG2 cancer cells, U87 cells, and HeLa cells and MCF-7 cells, indicating that decrotonylation of Ku80 K568cr is required for activation of DNA DSB repair." (PMID 40254688, 2025). "Moreover, the combination of IBC and BKC further increased γ-H2AX fluorescence in MCF-7 but not in BJ cells, which is consistent with their effect on cancer cell growth." (PMID 39887032, 2025). "Since phosphorylated H2AX is a marker of DNA damage, our findings suggested that roscovitine induces DNA damage in HPV+, but not HPV- cancer cells, which was undeniably verified utilizing the Comet assay, providing one possible mechanistic explanation for HPV+ HNSCC sensitivity." (PMID 27233076, 2016). "Interestingly, depletion of extracellular WISP-1 protein in established radioresistant cells directly induced a mass of γ-H2AX foci and obvious mitotic catastrophe, but depletion of extracellular WISP-1 protein in normal cancer cells did not have this effect." (PMID 24728101, 2014).
infection (81 papers, 2008 to 2026). The state of being infected such as from the introduction of a foreign agent such as serum, vaccine, antigenic substance or organism. "Taken together, these results indicate that D-Serine induced repression of natively encoded colibactin during infection of HeLa cells and led to a reduction in the formation of DSBs as measured by decreased phosphorylation of H2AX." (PMID 36908282, 2023). "While H2AX associates with the viral genome by 2 h following infection and with newly synthesized genomes, γH2AX appears to be excluded from viral replication compartments." (PMID 33563816, 2021). "As compared to Lyz2Cre/+ BMDMs (normal NHEJ), infection of Lig4loxP/loxP:Lyz2Cre/+ BMDMs (loss of NHEJ) with L. monocytogenes leads to augmented γ-H2AX formation." (PMID 28362262, 2017). "To determine whether the effects of EVA71 on γ-H2AX extend to related enteroviruses, we assessed the effects of infection with CA16 (associated with typical HFMD), CA6 (associated with atypical HFMD), and EVD68 (associated with respiratory illness)." (PMID 35067196, 2022). "Because VADs correlated strongly with γ-H2AX ChIP-seq sites identified on mock-infected cells as they progressed through S-phase, and on non-infected, HU-treated A9 cells, the predominantly identified γ-H2AX signal associated with MVM during infection very likely resides on cellular DNA." (PMID 30028293, 2018). "Given K. pneumoniae 1084 is a colibactin-producing K1 CC23 strain, we next examined whether the infection of 1084S caused DNA damages in the brain by detecting phosphorylation of histone H2AX, an indicator of double-strand DNA breaks." (PMID 28409125, 2017). "To this end, we tested organoids for phosphorylation of H2AX at serine 139 (γH2AX), a histone variant involved in detection of DSBs and recruitment of repair factors, and we quantified and mapped the number of γH2AX-positive cells after infection with the wild type and the ΔcdtB strain." (PMID 32963006, 2020). "Phospho-H2AX acts as a platform for hierarchical recruitment and retention of these phospho-proteins in a time-dependent manner during infection." (PMID 38433244, 2024). "Confocal microscopy showed the recruitment of the active form of DNA-PK (phospho-DNA-PK) to the DNA damage foci in the nucleus observed by the localization of the phospho-H2AX at different times of infection." (PMID 38433244, 2024). "To better understand the activation of the DDR pathway in LLC-MK2 cells infected with T. cruzi, we first examined the phosphorylation of H2AX at different times post-infection by immunofluorescence." (PMID 38433244, 2024). "Cell lysates were extracted 4 h post-infection and detection of γ-H2AX was determined by immunoblotting." (PMID 36908282, 2023). "We found that induction of DDR occurred following rAAV2.5T infection, which was characterized by the phosphorylation of replication protein A32 (RPA32) and histone variant H2AX (H2A histone family member X), as well as all three PIKKs: ATM, ATR, and DNA-PKcs." (PMID 37841417, 2023). "Inclusion of D-Serine during infection with Nissle 1917 resulted in a 2.75-fold reduction in γ-H2AX signal intensity compared to cells infected with untreated Nissle 1917 (P = 0.003)." (PMID 36908282, 2023). "Since both oxidative-induced and TT-induced DNA damage promotes H2AX phosphorylation, we performed additional experiments to assess the type of DNA damage induced in the colonic and hepatic tissues upon infection." (PMID 38274797, 2023). "The results revealed that PRV XJ5 and Ra infection increased the expression of γ-H2AX in PK15 cells compared with that in mock-infected cells at 18 and 24 hpi." (PMID 36951571, 2023).
infection (continued). "Infection promoted a significant increase in cells positive for the DDR marker γH2AX (a phosphorylated form of histone H2AX at serine 139) in both tissues in a toxin-independent manner." (PMID 38274797, 2023). "After 24 h of infection, the percentage of γ-H2AX-positive cells significantly increased, which indicated that PRV replication induced DDR." (PMID 36951571, 2023). "It was confirmed that siATR blocked the upregulation of γ-H2AX after EVA71 infection whereas siATM or siDNA-PK promoted the upregulation of γ-H2AX after EVA71 infection." (PMID 35067196, 2022). "At an MOI of 1, EVA71 obviously increased the levels of γ-H2AX at 24 h post infection in human RD cells." (PMID 35067196, 2022). "The results showed that EVA71 infection upregulated the expression of γ-H2AX at 24 h post infection in MRC-5 and HeLa cells." (PMID 35067196, 2022). "At increasing doses (0, 2, 4, 8, and 16 μM), the ATR inhibitor inhibited the upregulation of γ-H2AX induced by infection with EVA71; importantly, the ATR inhibitor also inhibited the expression of viral protein VP1." (PMID 35067196, 2022). "For this purpose, we selected MRC-5 (MOI = 2) and HeLa cells (MOI = 10) to further analyze the levels of γ-H2AX after infection with EVA71." (PMID 35067196, 2022). "Western blotting assays demonstrated that an increase in the dose of caffeine (1 or 2 mM) led to an obvious decrease in the levels of γ-H2AX and viral protein expression at 24 h post infection in a dose-dependent manner in RD cells." (PMID 35067196, 2022). "Infection with EVA71 increased the levels of γ-H2AX protein in cells over time (Figures 3c6 and 3c5 vs. 3c4)." (PMID 35067196, 2022). "H2AX phosphorylation (γH2AX) can be detected as early as 30-min post-infection in primary endothelial cells and colocalizes with viral DNA." (PMID 33484281, 2021). "In the same manner as phosphorylated H2AX, phosphorylated ATM was induced within 30 min post infection, and the inhibition of ATM activity caused a reduction of LANA expression, while knockdown of Chk1 and Chk2 did not affect LANA expression." (PMID 33425783, 2020). "At 20 h post-infection there was a significant difference in the H2AX phosphorylation induced by recurrent vs initial isolates obtained from all three patients." (PMID 31118484, 2019). "At 6 h post-infection, there was a significant difference in the H2AX phosphorylation induced by 45i vs 46r and by51i vs52r strains." (PMID 31118484, 2019). "In a dose-response experiment, γ-H2AX levels were strongly reduced in CAFs upon infection with an inducible CSL expression vector, even with a minimal CSL increase comparable with endogenous levels in HDFs." (PMID 31467287, 2019). "H2AX was phosphorylated earlier during infection (1.5–4.5 h), indicating DNA damage during this period." (PMID 30062089, 2018). "ChIP-seq analysis for γ-H2AX and BRCA1 demonstrated that DNA damage increased during infection, and MVM subsequently associated also with newly induced sites." (PMID 30028293, 2018). "Approximately a week after the infection, the cells were subjected to immunofluorescence on metaphase chromosomes to detect γ-H2AX." (PMID 28117327, 2017). "AdF35/Sur infection also induced γ-H2AX expression, a DNA damage marker, at 24 h, and expression of NBS-1, a marker for cellular DNA damage responses, was down-regulated upon Ad infection as reported." (PMID 29126418, 2017). "The phosphorylation of histone H2AX, a common marker of DNA damage, during lytic infection by HSV-1 is well established." (PMID 26817608, 2016). "Activation of ATM, phosphorylation of H2AX, and the recruitment of DNA repair factors to viral replication centers are observed upon infection with multiple DNA viruses, including SV40, HCMV, HSV-1, KSHV, EBV, MCPyV, and γHV68." (PMID 27310012, 2016). "To investigate interactions between pathogen infection and genome stress, we used γ-H2AX to monitor the extent of DNA damage in response to bacterial pathogens in Arabidopsis." (PMID 24699527, 2014).
infection (continued). "Transient infection of BALB/c normal liver cells with K. pneumoniae 1084 increased the phosphorylation of histone H2AX, indicating the induction of host DNA damage." (PMID 24852749, 2014). "At day 5 post infection, after brief puromycin selection, the rate of degradation of H2AX in parental and MCF10A/Her2 cells was measured by immunoblotting following inhibition of translation by emetine." (PMID 25252808, 2014). "We examined the γ-H2AX level in response to pathogen infections in the atrbohD and atrbohDF mutant plants." (PMID 24699527, 2014). "A low but constitutive presence of γ-H2AX was detected in the cpr5 mutant prior to pathogen infection." (PMID 24699527, 2014). "tomato (Pst) strain DC3000 and levels of γ-H2AX at various time points after infection were determined using an anti-γ-H2AX antibody." (PMID 24699527, 2014). "Because no obvious homologs of DNA-PK are present in nonvertebrates, our experiments suggest that plants have one or more kinases other than ATM, ATR or DNA-PK that can phosphorylate H2AX, and which do so in response to pathogen infection." (PMID 24699527, 2014). "Infected cellswere initially assayed for the expression of the earliest viral latency geneproduct, EBNA-LP (LP), and the DNA damage marker, γ-H2AX, at differenttimes post infection." (PMID 21147465, 2010). "Following infection, there is pan-nuclear activation of γ-H2AX and host proteins involved in DNA repair process the linear single-strand viral DNA to double-strand circular monomers and concatemers." (PMID 19888330, 2009). "However, overexpression of GSTM2 by AAV9-GSTM2 infection notably alleviated DNA damage, as evidenced by decreased γ-H2AX expression in PE-treated cardiomyocytes and inhibiting of 8-OHDG production and eccDNA release in mouse HF samples." (PMID 38037116, 2023). "In mock-infected cells, γ-H2AX presented stable expression from 12 to 30 h post infection." (PMID 35067196, 2022). "EVA71 might induce DNA single-strand breaks to activate the ATR pathway which is responsible for the formation of γ-H2AX after EVA71 infection whereas the activation of ATM or DNA-PK might be lowered after EVA71 infection." (PMID 35067196, 2022). "Therefore, after EVA71 infection, γ-H2AX was first upregulated in the nuclei, after which γ-H2AX was located in the cytoplasm." (PMID 35067196, 2022). "Importantly, after 12-h infection, γ-H2AX was still distributed in the nuclei of EVA71-infected cells (Figures 3c14 and 3c13), whereas at 24 h post infection, γ-H2AX was mainly distributed in the cytoplasm (Figure 3c15)." (PMID 35067196, 2022). "Hence, in this study, we investigated the location of γ-H2AX in the nucleus after infection with EVA71." (PMID 35067196, 2022). "Previous studies have shown that Ct infection can increase the phosphorylation level of H2AX and H2k9me3 in cervical epithelial cells, which were the hallmarks of DNA double-strand breaks (DSBs) and senescence-associated heterochromatin foci (SAHF), respectively." (PMID 34568091, 2021). "To test this hypothesis, we quantified H2AX phosphorylation in response to DNA damages after HeLa cell infection by E. coli SP15 and deletion mutants of speE and speG genes." (PMID 31578245, 2019). "However it remains possible that γ-H2AX and/or other DDR signaling proteins are directly associated with the viral genome during infection." (PMID 30028293, 2018). "This strongly implied, although does not prove, that the γ-H2AX identified associated with MVM during infection resides on cellular DNA." (PMID 30028293, 2018). "For the rhesus macaque monkey polyomavirus SV40, infection of permissive CV1 or BSC40 monkey cells causes activation of ATM signaling, H2AX phosphorylation and Mre11-Rad50-Nbs1 assembly with T-antigen together with other DDR-signaling proteins in viral replication foci." (PMID 28202068, 2017). "However, marked phosphorylation of H2AX is observed during MR766 infection of hNSCs – the disease-relevant target cells." (PMID 29022904, 2017).
infection (continued). "To interrogate the role of phosphorylated H2AX in infection of human fibroblasts by HSV-1 and HSV-2, we inhibited ATM and ATR activity using three approaches: chemical inhibitors of ATM or ATR kinase activity, siRNAs specific for ATM and ATR, and cell lines deficient in either ATR or ATM." (PMID 26817608, 2016). "Curiously, however, PAA did inhibit H2AX phosphorylation induced upon infection by HSV-2." (PMID 26817608, 2016). "To determine whether Arabidopsis ATR or ATM is required for the phosphorylation of H2AX in response to pathogen infection, we examined γ-H2AX levels in atr and atm single mutants and in atr atm double mutant plants." (PMID 24699527, 2014). "Likewise, in the case of Listeria, we show that downregulation of Mre11 or ATM or H2AX favors infection." (PMID 25340842, 2014). "Surprisingly (in light of the mutagenic nature of ROS in many settings), infection-associated AtrbohD- and AtrbohF-dependent ROS production is not required for pathogen-induced elevation of γ-H2AX." (PMID 24699527, 2014). "This technique also revealed higher levels of infection in 53BP1, H2AX and ATM knocked down cells." (PMID 25340842, 2014). "Infection-induced formation of γ-H2AX still occurred in Arabidopsis atr/atm double mutants, suggesting the presence of an alternative mediator of pathogen-induced H2AX phosphorylation." (PMID 24699527, 2014). "However, even though H2AX can be phosphorylated by other kinases later during infection, activated ATM is mostly located in HCMV RCs at these times pi, leaving open the possibility that ATM is influencing activities in these nuclear compartments." (PMID 21589897, 2011). "Approximately 60% of the infected cells wereγ-H2AX positive at 7 days post infection." (PMID 21147465, 2010). "Indeed the frequency of syncytia exhibiting the phosphorylation of ATM and that of the ATM substrate γ-H2AX was similar after infection with HIV-1 WT and HIV-1 IND64V." (PMID 18560558, 2008). "Thus, we investigated whether EVA71 induced DDR, and proved that infection with EVA71 upregulated γ-H2AX and induced DDR." (PMID 35067196, 2022). "Interestingly, the knockdown of α4 protein expression was associated with a loss of H2AX Ser139 phosphorylation and the subsequent infection with the control EGFP expressing adenovirus did not further alter the Ser139 phosphorylation status of H2AX." (PMID 33737606, 2021). "In vitro, it was found that P+ group could induce DNA damage in OSCC cells under short-term acute infection, which made γ-H2AX gradually accumulate with cell proliferation, activate the upstream signal molecule of ATR-CHK1, and increase the phosphorylation level of ATR and RPA2." (PMID 34660289, 2021). "Indeed, after infection of BMDMs with L. monocytogenes, DDR activation depends on TLR signaling, as BMDMs deficient in MyD88, a critical TLR adaptor protein, exhibit diminished γ-H2AX formation." (PMID 28362262, 2017). "To gain insights into the anti-proliferative pro-death activity of SMOX, we analyzed the phosphorylation of H2AX histone (γH2AX), a biomarker for double-strand breaks (DSBs), in RD and JR1 cells at 24, 48, and 72 h post-infection with pSMOX or pBABE." (PMID 36755974, 2023). "Unlike siDNA-PK and siATM, siATR inhibited the upregulation of γ-H2AX and VP1 upon infection with EVA71." (PMID 35067196, 2022). "The effect observed during infection is a higher expression of PCNA and phosphorylation of histone H2AX in both cell lines." (PMID 35677658, 2022). "In vitro, infection of Vero-E6 cells with SARS-CoV-2 induced senescence (SenTraGor), DNA damage (γ-H2AX) and increased cytokine (IL-1β, IL-6, CXCL8) and apolipoprotein B mRNA-editing (APOBEC) enzyme expression." (PMID 35086840, 2022).